LASP1 (LIM and SH3 protein 1)
Diseases named in the same sentence as LASP1 in open-access papers (continued):
Sharing a sentence is not in itself a finding about the gene and the disease.
pancreatic cancer (continued). "Other studies have found that ANLN could promote the progression of pancreatic cancer by inducing the up-regulation of EZH2 by mediating the mir-218-5p /LASP1 signaling axis." (PMID 31681575, 2019). "Whether LASP1 is involved in ANLN-induced pancreatic cancer progression is what we deal with in this study." (PMID 31395079, 2019). "Moreover, LASP1 re-expression partially reversed the effect of ANLN knockdown on pancreatic cancer cell migration and invasion." (PMID 31395079, 2019). "Therefore, vigorous research efforts are needed to further clarify whether PI3K/AKT axis contributed to LASP1-mediated pancreatic cancer cell growth and metastasis." (PMID 31395079, 2019). "Therefore, ANLN may promote pancreatic cancer cell progression and miR-218-5p/LASP1 signaling axis by mediating EZH2." (PMID 31395079, 2019). "In pancreatic cancer, ANLN depletion downregulates multiple cell-adhesion-related genes, particularly LIM and SH3 domain protein 1(LASP1), thereby impairing migration, invasion, and tumorigenic capacity." (PMID 41573677, 2025). "Based on the GENT database, we showed that both LASP1 and RUVBL1 gene expression were significantly upregulated in pancreatic cancer tissues and were positively correlated with ANLN expression." (PMID 31395079, 2019). "(A) Based on the GENT database, LASP1, RAB11B, RUVBL1 and MYO1B gene expression were analyzed in the pancreatic cancer tissues and normal pancreatic tissues." (PMID 31395079, 2019). "(B) There were significant Pearson correlations of ANLN with LASP1 and ANLN with RUVBL1 in the pancreatic cancer tissues and the normal pancreatic tissues." (PMID 31395079, 2019). "Thus, ANLN may promote pancreatic cancer cell progression by regulating LASP1." (PMID 31395079, 2019). "Thus, ANLN may regulate LASP1 expression and pancreatic cancer progression by miR-218-5p." (PMID 31395079, 2019). "ANLN-mediated pancreatic cancer invasion and migration, colony formation, cell proliferation may involve EZH2/miR-218-5p/LASP1 signaling axis." (PMID 37138854, 2023). "Taken together, ANLN may promote pancreatic cancer cell growth, migration and invasion by regulating EZH2/miR-218-5p/LASP1 signaling axis." (PMID 31395079, 2019). "Based on the GENT database, we showed that both LASP1 and RUVBL1 gene expression were significantly upregulated in pancreatic cancer tissues compared with that in normal pancreatic tissues, while RAB11B was not changed obviously, and MYO1B was significantly downregulated." (PMID 31395079, 2019). "(C) CCK-8 assay showed that LASP1 restoration partially reversed the effects of ANLN knockdown on pancreatic cancer cell proliferation, while RUVBL1 restoration did not reverse the effect of ANLN downregulation on pancreatic cancer cell proliferation." (PMID 31395079, 2019). "In addition, EZH2/miR-218-5p/LASP1 signaling axis might be involved in ANLN-mediated cell proliferation, colony formation, migration and invasion in pancreatic cancer." (PMID 31395079, 2019).
bladder cancer (10 papers, 2013 to 2024). "Several studies have linked overexpression of the LIM and SH3 domain protein 1 (LASP1) to progression of breast, colon, liver, and bladder cancer." (PMID 24980827, 2014). "Knockdown of LASP1 in prostate and bladder cancer cell lines also resulted in decreased MMP levels although with different impact." (PMID 27588391, 2016). "In molecular studies, miR-133a has been shown to directly regulate several metastasis-related oncogenes, including FSCN1 in bladder cancer, LASP1 in CRC, and CAV1 in head and neck squamous cell carcinoma." (PMID 25104873, 2014). "In this context, discrepancies between LASP-1 mRNA expression levels and protein levels has been reported in bladder cancer cell lines." (PMID 24386158, 2013). "In bladder carcinoma, luciferase reporter assays showed reduced luminescence intensity with miR-1, miR-133a, and miR-288 transfectants, suggesting cognate target sites in the 3′UTR of LASP1 for these miRNAs." (PMID 25622104, 2015). "LIM and SH3 protein 1 (LASP1) is a multifunctional cytoskeletal protein that modulates cell growth, migration, signal transduction, and invasion by interacting with its binding partners to facilitate the progression of cancers, including breast, colorectal, and bladder cancers." (PMID 38587834, 2024).
esophageal squamous cell carcinoma (9 papers, 2015 to 2025). Esophageal squamous cell carcinoma (ESCC) is a type of esophageal carcinoma (EC) that can affect any part of the esophagus, but is usually located in the upper or middle third. "Moreover LASP1 overexpression is observed in oral squamous cell carcinoma (OSCC), esophageal squamous cell carcinoma (ESCC), gastric cancer and pancreatic ductal adenocarcinoma (PDAC)." (PMID 25622104, 2015).
gastric cancer (9 papers, 2015 to 2024). A primary or metastatic malignant neoplasm involving the stomach. "LASP1 is an actin-binding protein, and overexpression of LASP1 is associated with poor prognosis in patients with gastric cancer." (PMID 37937197, 2023). "In gastric cancer, hypermethylation of DNA led to downregulation of miR-29b, which contributed to overexpression of LASP1." (PMID 31372094, 2019). "Also, LASP1 plays a crucial role in the growth and metastasis of gastric cancer and other cancers." (PMID 36970516, 2023). "For gastric cancer, the same has been shown in vitro using SGC7901/shLASP1 cells and was confirmed in SCID mice as tumorigenesis and metastasis were inhibited upon LASP1 knockdown." (PMID 25622104, 2015). "In fact, in gastric cancer and HCC multivariate analyses revealed, that cytoplasmic LASP1 expression is an independent prognostic factor of patients’ survival." (PMID 25622104, 2015).
lung carcinoma (9 papers, 2017 to 2023). "In accord with those findings, CERS6 and LASP1 were found to co-localize on lamellipodia in several lung cancer cell lines." (PMID 37345118, 2023). "MiR‐133a inhibits lung cancer cell proliferation in vivo and in vitro by targeting the LASP1 and TGF‐β/Smad3 signaling pathways." (PMID 36305754, 2023). "The present results provide evidence that CERS6, LASP1, and actin form a ternary complex in various lung cancer cell lines." (PMID 37345118, 2023). "The lung cancer cells were developed EMT by TGF-β1 accompanying LASP1 silence or overexpression using LASP1 shRNA lentivirus or LASP1 pcDNA, respectively." (PMID 34912481, 2021). "The gene and protein levels of LASP-1 were successfully silenced or overexpressed by LASP-1 shRNA lentivirus or pcDNA in TGF-β1-treated lung cancer cell lines, respectively." (PMID 34912481, 2021). "The aim of this study is to explore the essential role of LASP1 in TGF-β1-induced epithelial-mesenchymal transition (EMT) in lung cancer cells." (PMID 34912481, 2021). "In lung cancer metastasis, the role of LASP1 has only recently been explored and needs to be further studied." (PMID 34912481, 2021). "H‐E staining of the lung cancer tissue metastasis tumour nest confirmed that LASP1 expression from tumour nodules in the interference group was lower than that of the control group." (PMID 31793711, 2020). "In conclusion, miR‐133a acted as a tumor suppressor in lung cancer progression by regulating the LASP1 and TGF‐β/Smad3 signaling pathway." (PMID 33074595, 2020). "In this study, we explored the protein level and subcellular distribution of Lasp1 in both lung cancer tissues and cell lines, as well as their clinicopathological relevances." (PMID 29088849, 2017). "The results indicated that Lasp1 was positively expressed in all 10 cell lines and showed higher protein level in 9 lung cancer cells than in HBE cells." (PMID 29088849, 2017). "We speculated that, in lung cancer, LASP1 might be involved in the process of TGF-β1-mediated EMT and might affect the relevant transcriptional molecules in cell nuclei." (PMID 34912481, 2021). "In general, the research on the mechanism of LASP1 regulating lung cancer is still in its infancy." (PMID 34912481, 2021). "However, in lung cancer, little is explored about the correlation between LASP1 andTGF-β1-induced EMT, although it is observed that LASP1 promotes proliferation, migration, and invasion of NSCLC cell lines." (PMID 34912481, 2021). "Also, a study reported that LASP1 increases the expression of snail to induce EMT in lung cancer." (PMID 36670097, 2023). "Thus, the role of LASP1 in TGF-β1-induced EMT in lung cancer cells was investigated." (PMID 34912481, 2021). "As LASP1 could locate on focal adhesions (podosomes and invadopodia), the leading edges of lamellipodia (pseudopodia), and tips of filopodia, the cellular location hints the invasion and metastasis roles of LASP1 in lung cancer." (PMID 34912481, 2021). "However, the relationship of LASP1 with TGF-β1-mediated EMT in lung cancer has been rarely studied." (PMID 34912481, 2021). "The correlation between LASP1 and TGF-β1-mediated EMT has been little studied in lung cancer, although it has been reported in other cancers." (PMID 34912481, 2021). "Overall, this study identified the integral changes of TGF-β1-mediated EMT by LASP1, from signaling activation and nuclear expression of key signal molecules to EMT-related markers and biological functions in lung cancer cell lines in vitro." (PMID 34912481, 2021). "In this study, it is aimed to elucidate the role of LASP1 in the proliferation, invasion, migration, EMT, and nuclear expression of key molecules in lung cancer cell lines upon TGF-β1 stimulation." (PMID 34912481, 2021). "In vitro results reflected that LASP1 knockdown decreases the invasion, migration, and proliferation of TGF-β1-treated cells, while LASP1 overexpression further worsens the malignant behaviors of lung cancer cells." (PMID 34912481, 2021).
lung carcinoma (continued). "Taken together, the data in this study reveal that LASP1 might play a regulatory role in the TGF-β1-induced EMT process and might be a drug target upon EMT, affecting the initial and sustained stages in the metastasis of lung cancer cells." (PMID 34912481, 2021).
medulloblastoma (9 papers, 2012 to 2024). A malignant, invasive embryonal neoplasm arising from the cerebellum. "Treatment failure mainly occurs in children affected by metastases from high-risk medulloblastomas, which are characterized by aberrations of chromosome 17, mostly deletion of 17p and gain of 17q with LASP1 being one of the most upregulated genes on chromosome 17q in tumors with 17q gain." (PMID 25622104, 2015). "In line with this, it has been shown that miR-206 is downregulated in medulloblastoma tissues, and its increased expression decreased the cell viability and migration of medulloblastoma cells via the miR-206/LASP1 axis." (PMID 39010056, 2024). "LASP1 is expressed in virtually all normal tissues, but overexpressed in many cancer entities such as the aggressive pediatric brain tumor medulloblastoma as well as breast, ovarian and colorectal carcinoma." (PMID 24980827, 2014). "Up to this study, LASP1 has been depicted as a protein being significantly upregulated in numerous tumor entities: colon, bladder, prostate breast, liver, gastric, renal, oral malignant tumors as well as medulloblastoma." (PMID 26061439, 2015). "Besides studies on LASP1 in carcinomas, LASP1 was also investigated in leukemia and in medulloblastomas, the latter being one of the most common malignant pediatric brain tumors." (PMID 25622104, 2015). "Additionally in meningioma, an effect of LASP1 overexpression can be assumed as our comprehensive expression analysis revealed a highly significant (p<0.001) overexpression of LASP1 in this entity as well as in medulloblastoma." (PMID 25622104, 2015). "LASP1 knockdown experiments in medulloblastoma cell lines DAOY, UW228-2, and D283 showed a strong reduction of cell migration and proliferation, and an increased cell adhesion pointing to an oncogenic role of LASP1 in medulloblastoma." (PMID 25622104, 2015).
lymph node metastasis (8 papers, 2007 to 2025). "LASP1 (LIM and SH3 protein 1), a gene associated with lymph node metastasis and poor clinical prognosis, is upregulated in several malignant tumors, underscoring its oncological significance." (PMID 40538852, 2025). "LASP1 has been shown to promote invasion and metastasis; particularly, LASP1 overexpression in pancreatic ductal adenocarcinomas was found to be significantly associated with lymph node metastasis and poor overall survival." (PMID 27799870, 2016). "In patients with PTC, high levels of LASP1 were associated with a lower overall survival, and correlated with the TNM stage and lymph node metastasis." (PMID 39449799, 2024). "The mRNA expression of LASP1 in the HNSCC tissues was associated with lymph node metastasis (P = .0482) and TNM stage (P = .0174) but not age, sex or smoking history." (PMID 31793711, 2020).
non-small cell lung carcinoma (7 papers, 2017 to 2023). A group of at least three distinct histological types of lung cancer, including non-small cell squamous cell carcinoma, adenocarcinoma, and large cell carcinoma. "Previous studies had confirmed that Lasp1 was significantly overexpressed in multiple malignant tumors including non-small-cell lung cancer (NSCLC) and enhanced tumor proliferation, invasion and metastasis." (PMID 29088849, 2017). "In non-small cell lung cancer (NSCLC), LASP1 directly bound to FAK and enhanced the phosphorylation of FAK and AKT, thereby inducing cell proliferation and invasion." (PMID 31395079, 2019). "Lasp1 (LIM and SH3 domain protein 1) promotes tumor proliferation and invasion in multiple cancer entities including non-small cell lung cancer (NSCLC)." (PMID 29088849, 2017). "MiR-29a was claimed to have the ability to decreased proliferation in non-small-cell lung cancer (NSCLC), via negatively correlating with LIM and SH3 domain protein 1 (LASP1), a cAMP- and cGMP-dependent signaling protein and a member of the nebulin family of actin-binding proteins." (PMID 29217524, 2018). "In non-small cell lung cancer samples, the expression of SE-lncRNA LINC01503 and LIM and SH3 domain protein 1 (LASP1) was increased, while the expression of miR-342-3p was downregulated, suggesting that SE-lncRNA LINC01503 may competitively bind LASP1 with miR-342-3p." (PMID 37501079, 2023).
colon cancer (6 papers, 2016 to 2023). "For example, epigenetically regulated miR-145 suppresses colon cancer invasion and metastasis by targeting LASP1." (PMID 29416759, 2018). "Furthermore, it is reported that PUS7 can regulate the metastatic ability of colon cancer cells through the HSP90/PUS7/LASP1 axis." (PMID 37420297, 2023). "In addition, studies have shown that PUS7 can influence colon cancer cell metastasis by regulating LASP1, but does not affect tumor cell proliferation." (PMID 37420297, 2023).
head and neck squamous cell carcinoma (6 papers, 2014 to 2024). A squamous cell carcinoma that arises from any of the following anatomic sites: lip and oral cavity, nasal cavity, paranasal sinuses, pharynx, larynx, and salivary glands. "In a recent study, LASP1 depletion was shown to be detrimental to the proliferation of head and neck squamous cell carcinoma (HNSCC) cells, all of which were HPV-." (PMID 38789663, 2024). "miR-203 controls head and neck squamous cell carcinoma metastasis by targeting a network of prometastatic proteins, including LASP1, SPARC, and NUAK1." (PMID 29262657, 2017). "For example, a 7-mRNA signature (AATF, APP, GNPDA1, HPRT1, LASP1, P4HA1 and ILF3) of head and neck squamous cell carcinoma (HNSCC) shows a moderate predictive ability for 5-year OS (AUC for training set, 0.75; testing set, 0.66)." (PMID 31396442, 2019).
liver cancer (6 papers, 2016 to 2024). An epithelial or non-epithelial malignant neoplasm that arises from the liver. "Furthermore, we showed that the LASP1 K75A mutation had little effect on the IC50 values of sorafenib in liver cancer cells." (PMID 36670097, 2023). "In contrast, we demonstrated that overexpression of TRIM15 WT but not the catalytically dead mutant promoted the ubiquitination of LASP1 in liver cancer cells." (PMID 36670097, 2023). "Together, our data suggested that LASP1 is the key mediator through which TRIM15 modulates sorafenib sensitivity in liver cancer cells." (PMID 36670097, 2023). "Previous studies have shown that CYTOR can promote liver cancer progression through regulation of the miRNA-125a-5p/LASP1 axis and miR-125b/SEMA4C axis." (PMID 36452343, 2022). "We found that TRIM15 interacted with LASP1 in liver cancer cells." (PMID 36670097, 2023). "Thus, our results indicated that TRIM15 regulates the nuclear translocation of LASP1 in liver cancer cells." (PMID 36670097, 2023). "Similarly, we found that knockdown of TRIM15 decreased the total ubiquitination and K63-linked ubiquitination but not K48-linked ubiquitination of LASP1 in liver cancer cells." (PMID 36670097, 2023). "Moreover, we demonstrated that TRIM15 induced the nuclear translocation of LASP1 by mediating its K63-linked polyubiquitination, which modulated sensitivity to TKIs by increasing the phosphorylation of AKT and the expression of Snail in liver cancer cells." (PMID 36670097, 2023). "Thus, we examined whether LASP1 is the key mediator of TRIM15-induced TKI resistance in liver cancer cells." (PMID 36670097, 2023). "Taken together, these data suggested that the ubiquitination of LASP1 mediated by TRIM15 promoted LASP1 nuclear translocation to activate the AKT signaling pathway, which was responsible for inducing sorafenib resistance in liver cancer cells." (PMID 36670097, 2023). "Moreover, we presented novel mechanisms for LASP1 and SYVN1 to be involved in HBX-mediated GLUD1 inhibition in HBV-induced liver cancer." (PMID 38587834, 2024). "LASP1 overexpression has been reported in HBV-related HCC, and our previous works have indicated that HBX was responsible for the increase of this protein in liver cancer." (PMID 33722250, 2021).
triple-negative breast carcinoma (6 papers, 2012 to 2025). An invasive breast carcinoma which is negative for expression of estrogen receptor (ER), progesterone receptor (PR), and human epidermal growth factor receptor 2 (HER2). "Here we report that argonaute 2 (Ago2), a protein with central involvement in RNAi, associates with LASP1 in triple-negative breast cancer (TNBC) cells." (PMID 32872485, 2020). "The nuclear LASP1 then interacts with Snail1 in triple-negative breast cancer (TNBC) cell lines." (PMID 32825729, 2020). "More specifically, inhibiting the interaction between LASP1 and eIF4A may be one approach to sensitize triple-negative breast cancer cells to other inhibitors." (PMID 31106142, 2019).
breast tumor (5 papers, 2007 to 2021). "We investigated the effect of LASP1, a newly identified protein in invadopodia, on expression, secretion and activation of MMPs in invasive breast tumor cell lines." (PMID 27588391, 2016). "The increased expression of LASP-1 in breast tumours correlates with high rates of nodal-metastasis and refers to a possible relevance as a prognostic marker." (PMID 18419822, 2008). "Consistent with the high expression of LASP-1 in breast tumors recent data demonstrated the functional significance of LASP-1 for cancer metastasis." (PMID 17956604, 2007). "We therefore performed a retrospective study (January 1985 until December 2007) with samples of 177 archival cases of confirmed histological diagnosis of invasive breast carcinomas to evaluate the long-term survival of breast tumour patients in relation to nuclear and cytoplasmic LASP-1-positivity." (PMID 20461080, 2010).